MBP (myelin basic protein)
Diseases named in the same sentence as MBP in open-access papers (continued):
Sharing a sentence is not in itself a finding about the gene and the disease.
Tremor (2 papers, 2018 to 2021). An unintentional, oscillating to-and-fro muscle movement about a joint axis. "The severity of motor phenotype also varied greatly across the different MBP-aSyn lines, with severe tremor, ataxia, seizures and premature death in the highest expressing line (high expressor line 29, MBP29) to mild tremor and variable motor impairment in intermediate and lower expressing lines." (PMID 34613484, 2021).
Wolfram syndrome (2 papers, 2016 to 2021). Wolfram syndrome (WS) also known as DIDMOAD, is a neurodegenerative disorder characterized by type I diabetes mellitus (DM), diabetes insipidus (DI), sensorineural deafness (D), bilateral optical atrophy (OA) and neurological signs. "Biomarkers for neurodegeneration, such as neurofilament light chain and myelin basic protein, have been assessed in patients with Wolfram syndrome before." (PMID 34185708, 2021). "Thus, myelin basic protein may be a neuropathophysiologically meaningful biomarker of disease severity in Wolfram syndrome." (PMID 26888576, 2016).
alcohol dependence (1 paper, 2019). Physical and psychological dependence on alcohol. "Additionally, adolescent binge drinking or adult alcohol dependence induction in rats caused a reduction in the white matter of the anterior corpus callosum, as well as degradation of myelin basic protein in the PFC." (PMID 31456662, 2019).
amblyopia (1 paper, 2015). Decreased vision that results from abnormal visual development. "The timing of the shift to more Classic-MBP corresponds with the end of the sensitive period for development of amblyopia in children." (PMID 25964736, 2015). "In this study, we found that the shift from more Golli- to more Classic-MBP in human visual cortex coincides with the end of the sensitive period for development of amblyopia." (PMID 25964736, 2015).
anterior uveitis (1 paper, 2012). Inflammation of the iris and anterior chamber of the eye. "In another animal model, myelin basic protein-specific T helper cells induced experimental anterior uveitis." (PMID 23213530, 2012).
aortic aneurysm (1 paper, 2021). A ruptured aneurysm located in the wall of the proximal portion of the descending aorta proceeding from the arch of the aorta. "The biological relevance of FRMD6, GNG2 and MBP with respect to the development of aortic aneurysms is unclear at this time." (PMID 34469433, 2021).
Atrophy (1 paper, 2008). Any weakening or degeneration, especially through lack of use. "Since NF-H, MAP2 and myelin basic protein (MBP) are substrates of calpain, and calpain is known to be involved in Aβ-induced axonal atrophy, expression levels of calpain and calpastatin were measured." (PMID 18706097, 2008).
autoimmune neuropathies (1 paper, 2022). "Furthermore, T-cell mediated autoimmune neuropathies, including the rat model for Guillain–Barre syndrome (GBS), induced by immunization with immunodominant MBP peptides causes pain." (PMID 35073943, 2022).
avian influenza (1 paper, 2019). Infection of domestic and wild fowl and other birds with influenza A virus. "MBP-tagged avian influenza M2 protein has been developed as a coating antigen in the M2e-MBP ELISA method for differentiating avian influenza infected chickens from vaccinated ones." (PMID 30606183, 2019).
axonal neuropathy (1 paper, 2020). Any nerve disorder affecting the axon of a nerve. "Immunohistochemical study for peripherin in association with anti-MBP and anti-NF-H antibodies showed a markedly increased expression of peripherin and NF-H in the proband compared to a CMT2A patient (MFN2R94W, axonal neuropathy control) and a healthy control." (PMID 32326241, 2020).
brain inflammation (1 paper, 2022). "Studies have shown that the MBP-specific CD8+ T cells could exacerbate brain inflammation." (PMID 36211343, 2022).
brain tumor (1 paper, 2015). "Thus, it was hypothesized that the onset of a metastatic brain tumor damages the blood-brain barrier, causing myelin basic protein to enter the blood, subsequently increasing the levels of myelin basic protein in the serum." (PMID 25667676, 2015). "The trend line is flat and the R2 value is very low, indicating that the size of the metastatic brain tumor has only a small effect on the serum levels of myelin basic protein." (PMID 25667676, 2015).
cardiopulmonary arrest (1 paper, 2013). "We also carried out, to our knowledge, the first comparative study of serum levels of NSE, S100β, and MBP in critically ill infants and children after TBI, AHT, and cardiopulmonary arrest." (PMID 23637695, 2013).
Cerebellar atrophy (1 paper, 2022). Cerebellar atrophy is defined as a cerebellum with initially normal structures, in a posterior fossa with normal size, which displays enlarged fissures (interfolial spaces) in comparison to the foliae secondary to loss of tissue. "Furthermore, treatment with bimoclomol improved MBP expression, prevented cerebellar atrophy and preserved cerebellar weights at wild-type weights in a separate cohort of Npc1−/− mice; these effects were blocked by co-administration with the Fyn kinase inhibitor, saracatinib." (PMID 36455410, 2022).
cerebral malaria (1 paper, 2025). A sequestration of Plasmodium falciparum in the brain, which can cause coma and/or seizures. "A recent study applied network analysis and differential expression to whole-blood profiles, highlighting nine key host genes (including MBP, SAMSN1, PSMF1, SLC39A8) strongly linked to cerebral malaria." (PMID 41002937, 2025).
cervical cancer (1 paper, 2024). A primary or metastatic malignant neoplasm involving the cervix. "The reprogramming-related genes, including transcription factors (CJUN), myelin genes (MBP), neurotrophic factors and receptors (BDNF, NGFR) and axonal regenerative marker (GAP43) were significantly elevated upon RSC96 cells co-cultured with cervical cancer cells." (PMID 39214988, 2024).
Chagas disease (1 paper, 2025). A parasitic infection caused by Trypanosoma cruzi. "The significance of the response of CD4+ T cells from Chagas patients that display DERAA to MBP is unclear, but it is tempting to hypothesize that this response might be associated with auto-reactivity in Chagas disease." (PMID 40391216, 2025).
Cirrhosis (1 paper, 2020). A chronic disorder of the liver in which liver tissue becomes scarred and is partially replaced by regenerative nodules and fibrotic tissue resulting in loss of liver function. "Thus, it is likely that endothelial cell dysfunction during cirrhosis, characterized by poor permeability of liver sinusoids, is most likely partially caused by decreased MBP-stimulated production of NO." (PMID 32089540, 2020). "Another finding of this study is that cirrhosis down-regulates MBP, the main component of myelin sheaths which are significantly decreased during cirrhosis." (PMID 32089540, 2020). "Low levels of NEP and MBP in human cirrhosis may also decrease the hepatic clearance of Aβ delivered by the blood, leading to its increased plasma levels in cirrhotic patients." (PMID 32089540, 2020). "In cirrhosis, impaired synthesis of MBP, which mimics the effects of Aβ in increasing the production of NO may further reduce sinusoidal permeability and damage hepatic nerves." (PMID 32089540, 2020).
colon cancer (1 paper, 2023). "Accordingly, both technologies reported the overexpression of STIM1, MBP, SEPTIN9, and SEPTIN10 and the downregulation of CRACR2A, ORMDL3, SARAF, SEPTIN3, and SEPTIN6 in colon cancer cells." (PMID 36900391, 2023).
Constipation (1 paper, 2024). Infrequent or difficult evacuation of feces. "In conclusion, we have demonstrated that MbP-SFF and MbP-SFV improve intestinal motility in mice with loperamide-induced constipation." (PMID 38998543, 2024). "However, MbP-SFF and MbP-SFV suppressed the inflammation induced by constipation." (PMID 38998543, 2024).
cysticercosis (1 paper, 2023). "India ink staining, Cysticercosis antibody, the MycoDot test, the FTA-ABS test, aquaporin-4 (AQP4-IgG), myelin oligodendrocyte glycoprotein (MOG) antibody and myelin basic protein (MBP) antibody in the CSF were negative." (PMID 37248444, 2023).
developmental delays (1 paper, 2022). "The region related to developmental delays and abnormal cerebral white matter development is 18q22.3q23, and the possible related pathogenic genes are ZNF236, ZNF516, MBP, GALR1 and lOC284276." (PMID 36123715, 2022).
Dystonia (1 paper, 2016). An abnormally increased muscular tone that causes fixed abnormal postures. "In vivo assessment of optic nerve myelination at disease end-stage showed normal density of myelinated axons and myelin thickness in optic nerve, as well as normal expression levels of CNPase, MOG and MBP in both spinal cord and cerebral cortex in animals with dystonia muscolorum." (PMID 26886550, 2016).
enteritis (1 paper, 2023). Inflammation of the small intestine. "The interesting fact is that MBP could alleviate enteritis induced by soybean meal in the diet of Atlantic salmon and has no negative effect on the intestinal structure of largemouth bass." (PMID 36830467, 2023).
fetal growth restriction (1 paper, 2019). A fetus that does not grow beyond the 10th percentile of conventionally accepted weight for gestational age. "Uterine artery ligation IUGR induced models have been widely used to approach white matter damage linked to perinatal impairments such as prematurity or fetal growth restriction observing a similar reduction in MBP density in the corpus callosum and the cingulum, sign of myelination defect." (PMID 30800096, 2019).
fibrosis (1 paper, 2024). the formation of excess fibrous connective tissue in an organ or tissue in a reparative or reactive process. "In line with this, we found an increased ACE, MMP2, and MMP7 mRNA expression, but also reduced APEH, ECE1, MBP, and NEP in samples with an advanced fibrosis grade." (PMID 39201455, 2024).
fluorosis (1 paper, 2022). "The F dose of 50 mg/L was also capable of promoting tissue alterations as those animals showed reduced Purkinje cell density and MBP immunostained area fraction, which may indicate high doses of F as a risk to the environmental health of endemic fluorosis regions." (PMID 35955690, 2022).
frontotemporal dementia (1 paper, 2025). Frontotemporal dementia (FTD) comprises a group of neurodegenerative disorders, characterized by progressive changes in behavior, executive dysfunction and language impairment, as a result of degeneration of the medial prefrontal and frontoinsular cortices. "Of note, some studies have reported CSF MBP as being elevated in ALS, especially in those patients with frontotemporal dementia." (PMID 39748876, 2025).
Glucose intolerance (1 paper, 2023). Glucose intolerance (GI) can be defined as dysglycemia that comprises both prediabetes and diabetes. "Interestingly, we found an association between the glucose tolerance test area under the curve (GTT-AUC) and levels of MBP area density when pooling both sexes (linear regression, r2 = 0.2365, p = 0.0017), wherein worse glucose intolerance was associated with lower myelin coverage." (PMID 37208759, 2023).
Granuloma (1 paper, 2017). A compact, organized collection of mature mononuclear phagocytes, which may be but is not necessarily accompanied by accessory features such as necrosis. "Wagner and colleagues also described eosinophils infiltration and deposit of MBP on P. brasiliensis yeast cells in granulomas of patients with PCM." (PMID 28489854, 2017).
Haemophilia A (1 paper, 2025). "This is further underscored by promising results in related models, such as MOG-specific CAR-Treg and MBP-specific TCR-Treg for MS as well as the FVIII-specific CAR-Treg and FVIII-specific TCR-Treg to tolerate rFVIII in Haemophilia A patients." (PMID 41256853, 2025).
hemorrhage (1 paper, 2025). Loss of blood from the vascular compartment to the exterior or into nonvascular body space as a result of rupture or severance of the blood vessels. "Additionally, triple immunostaining with NeuN, MBP, and MAG confirmed that knocking out Lcn2 in microglia effectively enhances neuronal myelin recovery at the hemorrhage site during the chronic phase of ICH in mice." (PMID 40225581, 2025).
hepatocellular carcinoma (1 paper, 2022). A malignant tumor that arises from hepatocytes. "To test whether treatment with MBP-11901 induces the apoptosis of hepatocellular carcinoma cells, we evaluated the levels of protein expression of apoptosis markers in HepG2 cells, such as cleaved PARP1 and active caspase-3." (PMID 35454900, 2022).
HIV-1 infection (1 paper, 2022). The type species of lentivirus and the etiologic agent of acquired immunodeficiency syndrome (AIDS). "HIV-1 infection can cause the production of various natural autoantibodies, including catalytic antibodies hydrolyzing DNA, myelin basic protein, histones, HIV-integrase, HIV-reverse transcriptase, β-casein, serum albumin, and some other natural substrates." (PMID 35335016, 2022).
hyperhomocysteinemia (1 paper, 2021). A serious metabolic condition caused by mutations in the MTHFR gene, medications, or nutritional deficiency. "Hyperhomocysteinemia may lead to hypomethylation of MBP, which reduces its hydrophobicity and stability, thus leading to structural instability and degeneration and loss of the myelin sheath, with an adverse impact on disease progression." (PMID 34122309, 2021).
Hypoglycemia (1 paper, 2025). A decreased concentration of glucose in the blood. "While lactate could completely rescue myelination in hypoglycemia in slices from WT mice, the HCAR1 KO slices failed to fully restore myelination (%MBP/Control: WTHG_Lactate 89 ± 22, KOHG_Lactate 61 ± 28, pHG_LactateWT-KOp < 0.001)." (PMID 40345852, 2025).
idiopathic scoliosis (1 paper, 2023). A scoliosis with no known cause. "Our data on 2 patients with CP, 10 patients with idiopathic scoliosis, 2 patients with CP/scoliosis and 10 healthy controls, show that gene and protein expression for MBP or FFARs was lower in patients with CP and scoliosis than in controls, but the levels were lowest in subjects with CP/Scoliosis." (PMID 37538811, 2023).
ileus (1 paper, 2024). Decrease in peristalsis in the absence of a mechanical bowel obstruction. "A significant reduction in the rate of ileus occurrence was observed in the groups that received bowel preparation, with the OA and MBP + OA groups showing a significant reduction in the rate of ileus occurrence, as well as a shorter hospital stay." (PMID 39544841, 2024).
Insulin resistance (1 paper, 2020). Increased resistance towards insulin, that is, diminished effectiveness of insulin in reducing blood glucose levels. "In a study carried out in USA, MBP has been associated with poor insulin secretion, and MEP and MMP to insulin resistance assessed by Homeostatic model assessment of insulin resistance (HOMA-IR) index." (PMID 32764471, 2020).
intracranial aneurysm (1 paper, 2020). "Concentration of MBP in peripheral blood after intracranial aneurysm rupture reflects the severity of the brain parenchymal damage (due to surgery or ICH) and correlates with the treatment outcome." (PMID 31915942, 2020). "The concentration of MBP in peripheral blood after intracranial aneurysm rupture reflects the severity of the brain tissue injury (due to surgery or ICH) and correlates with the treatment outcome." (PMID 31915942, 2020).
Krabbe disease (1 paper, 2017). A lysosomal disorder that affects the white matter of the central and peripheral nervous systems. "Importantly, DEDA attenuated the psychosine-induced decrease in expression of MBP and MOG as well as vimentin supporting the idea that astrocyte function as well as oligodendrocyte myelination state is altered in Krabbe disease." (PMID 29095858, 2017).
leukemia (1 paper, 2021). A malignant (clonal) hematologic disorder, involving hematopoietic stem cells and characterized by the presence of primitive or atypical myeloid or lymphoid cells in the bone marrow and the blood. "In another example, CLB and CPT were conjugated to a 13-meric myelin basic protein (MBP)-derived peptide to form a multi-warhead PDC for TDD in a leukemia cell culture model." (PMID 33562300, 2021).
liver cirrhosis (1 paper, 2023). "However, the presence of comorbid factors such as co-abuse with tobacco or liver cirrhosis, can preclude causal associations of MBP in AUD studies." (PMID 37344865, 2023).
liver fibrosis (1 paper, 2017). "Balb/C mice were given an abdominal injection of MBP-CssPLA2 to detect whether the protein could activate hepatic stellate cells in vivo, and cause accumulation of collagen which leads to liver fibrosis." (PMID 28302166, 2017). "MBP-CssPLA2 could activate hepatic stellate cells which could lead to liver fibrosis." (PMID 28302166, 2017).
malaria (1 paper, 2021). Malaria is a serious and sometimes fatal disease caused by a parasite that commonly infects a certain type of mosquito which feeds on humans. "SAMSN1, SLC39A8, SMPDL3A, and FABP5 were positively correlated with malaria phenotype/severity and showed an upregulation in the CM group compared with healthy controls, while MBP, SPSB3, PSMF1, SHARPIN, EIF3B were negatively correlated with malaria severity and downregulated in the DEG." (PMID 33942992, 2021). "Within the nine genes, five genes (MBP, SAMSN1, PSMF1, SLC39A8, and EIF3B) were previously found to be involved in malaria, and the remaining four genes (SMPDL3A, FABP5, SPSB3, and SHARPIN) were identified for the first time in the current study." (PMID 33942992, 2021). "Conversely, the other five key genes (MBP, SPSB3, PSMF1, SHARPIN, and EIF3B) were negatively correlated with malaria severity and decreased in CM." (PMID 33942992, 2021).
medulloblastoma (1 paper, 2019). A malignant, invasive embryonal neoplasm arising from the cerebellum. "Cooperative signaling responding to Smo and EGFR receptor co-activation was previously observed in medulloblastoma cells treated with Gefitinib and Clobetasol action on MBP has been attributed to Smo and/or GR activation." (PMID 31390799, 2019).
memory impairment (1 paper, 2019). "A significant relationship was found 1 month after HI between MBP signal intensity in EC and the severity of hemiparesis, as assessed by CRT (R = 0.39, t = 2.6, p < 0.05), and between MBP signal intensity in CX and the severity of memory impairment, as assessed by NOR (R = 0.44, t = 2.6, p < 0.05)." (PMID 31611802, 2019).
morphea (1 paper, 2022). "This suggests a relationship between MBP autoantibodies, cutaneous inflammation, and symptoms associated with morphea." (PMID 35073943, 2022). "Our study has identified anti-MBP as a novel antibody associated with morphea due to its increased expression in morphea." (PMID 35073943, 2022). "Further studies are warranted to determine whether MBP antibodies, or other autoantibodies are present in sera prior to the clinical development of morphea." (PMID 35073943, 2022). "Given the observed autoreactivity to MBP in morphea cases, we aimed to determine whether inflammation was present in the perineural area of morphea skin lesions, which likely contributes to clinical symptoms of the disease such as pain." (PMID 35073943, 2022). "We next determined whether there were any clinical parameters that distinguished morphea patients with high serum titer MBP autoantibodies compared to morphea patients that did not have these serum autoantibodies." (PMID 35073943, 2022).
Morton Neuroma (1 paper, 2025). Swelling and inflammation of the nerve between the ends of the metatarsal bones at the base of the toes. "Corrected mean gray values and area fractions of MBP were reduced in nerves from patients with Morton's neuroma compared with control nerves, indicative of demyelination." (PMID 39588776, 2025).
motor neuron disease (1 paper, 2014). "Increases in slow myosin light chains and the troponin complex and a decrease in fast MBP (myosin-binding protein) probably reflect the initial preferential loss of the fast type of neuromuscular synapses in motor neuron disease." (PMID 24895011, 2014).